CTAG1B (cancer/testis antigen 1B)
Synonyms: CT6.1; LAGE-2; CTAG; CTAG1; ESO1; LAGE2A; LAGE2B; NY-ESO-1
Tractability: Small molecule: a structure with a bound ligand is known. PROTAC: ubiquitination databases record sites on it. Other modalities: a drug acting on it is in phase 2 or 3 trials.
Gene: Protein-coding gene on chromosome X (154,617,609 to 154,619,282, reverse strand). Ensembl gene ENSG00000184033.
Subcellular location: Cytoplasm
Subcellular location (Human Protein Atlas): Golgi apparatus; Vesicles
Gene Ontology:
Molecular function: identical protein binding; protein binding
Biological process: tRNA threonylcarbamoyladenosine metabolic process
Cellular component: cytoplasm
Homologues: Orthologues: rat Ctag2l1 (31% identical), mouse Ctag2l1 (29% identical), mouse Ctag2l2 (28% identical), rat Ctag2l2 (28% identical), mouse Ctag2 (26% identical), rat Ctag2 (24% identical), tropical clawed frog lage3 (19% identical), Drosophila melanogaster Tcs6 (13% identical). Paralogues in human: CTAG1A (100% identical), CTAG2 (86% identical), LAGE3 (34% identical).
Diseases named in the same sentence as CTAG1B in open-access papers:
CTAG1B is named in the same sentence as 22 diseases in open-access papers, as found by Europe PMC text mining. Sharing a sentence is not in itself a finding about the gene and the disease. The quoted sentences say what the papers report.
melanoma (8 papers, 2012 to 2025). A malignant, usually aggressive tumor composed of atypical, neoplastic melanocytes. "CD133+ CSCs in melanoma, which display elevated levels of MAAs like CTAG1B, are particularly susceptible to recognition by specific T cells." (PMID 40399946, 2025). "NY-ESO-1 is another CTA encoded by the CTAG1B gene located on chromosome Xq28 and is widely detected in melanoma, lung, ovarian, breast, and prostate cancer, as well as in normal testis tissue." (PMID 37509276, 2023). "In melanoma cells the CTAG1B/A protein is found in complexes with MAGEC1, another cancer testis antigen protein and a putative transcription factor, which is consistent with the narrow window of expression of both proteins in differentiating germ cells." (PMID 35664317, 2022). "Ctag1b/a is found in approximately one third of all melanoma, lung, and esophageal tumors, from which it was first isolated, as well as in liver, gastric, prostate, ovarian and bladder cancers." (PMID 35664317, 2022). "We further investigated ROPN1, ROPN1B and CTAG1B gene expression across different stages of disease and genders in melanoma." (PMID 33918976, 2021). "Arguably, the prototype CTAg is NY-ESO-1 (CTAG1A or identical gene copy CTAG1B), which induces spontaneous cellular and humoral immune responses in melanoma and other cancers." (PMID 33918976, 2021). "Another positively correlated antigen in melanoma is the CT gene NY-ESO-1 (CTAG1B), which was reported to be an effective vaccine antigen in a recent study." (PMID 27549193, 2016). "Vaccines using peptides derived from NY-ESO-1 (CTAG-1B) have shown clinical benefits in patients with melanoma." (PMID 22481966, 2012). "Shown in red are samples of advanced sarcoma types as well as melanomas that express ctag1b/a." (PMID 35664317, 2022). "With the exception of sarcoma, melanoma and CD133 positive glioblastoma samples, ctag1b/a, is randomly re-activated in most samples examined and does not follow any pattern, that is, characteristic of stage or tumor type." (PMID 35664317, 2022). "In melanoma, tumor cells typically express MAAs such as gp100, MAGE-A (Melanoma antigen family A), MART-1 (Melanoma antigen recognized by T cells 1), and CTAG1B (Cancer/testis antigen 1B), which attract MAA-specific CTLs for targeted destruction." (PMID 40399946, 2025). "Target analysis from these trials revealed that cancer-testis antigens were frequently studied, with cancer-testis antigen 1B (CTAG1B, also known as NY-ESO-1) emerging as a prominent target in STS and showing notable relevance in NSCLC, esophageal cancer, melanoma, liver cancer, and ovarian cancer." (PMID 39439803, 2024). "Thus, in three melanoma studies (GDS 1375, GDS 1965, and GDS1078) ctag1b/a is re-activated in 33% of samples." (PMID 35664317, 2022). "Similarly, gene expression of ROPN1 and ROPN1B was also commonly detected in a melanoma patient cohort accessed via the TCGA (ROPN1: 98.9%, ROPN1B: 98.7% vs. CTAG1B: 68.2%)." (PMID 33918976, 2021). "We assessed expression of ROPN1B, NY-ESO-1 (single protein from CTAG1A or CTAG1B genes), MLANA and SOX10 (used here as a melanoma tumour marker) at the protein level by multispectral immunohistochemistry on melanoma tissue microarrays (TMAs) comprising two or three cores from 61 patient tumours." (PMID 33918976, 2021). "CTAG1B, BRCA2, and SPAG8 have been previously shown to induce humoral immune response in BC and other cancer patients, ANKRD30BL and COPS4 were previously found to elicit autoantibody response in gastric and thyroid cancer and melanoma." (PMID 30515157, 2018). "We further evaluated the gene expression levels of ROPN1, ROPN1B, CTAG1B (identical gene copy to CTAG1A for which no gene expression data is available), TYR and MLANA in 472 additional melanoma samples using data accessible via The Cancer Genome Atlas (TCGA)." (PMID 33918976, 2021).
esophageal cancer (3 papers, 2019 to 2024). A primary or metastatic malignant neoplasm involving the esophagus. "The gene encoding New York’s esophageal squamous cell carcinoma 1 (NY-ESO-1), also known as cancer/testis antigen 1B (CTAG1), is a prototype of the cancer–testis (CT) gene family that was initially separated from esophageal cancer." (PMID 30656409, 2019). "Additionally, NY-ESO-1, which is also known as cancer/testis antigen 1B (CTAG1), is a prototypical member of the cancer-testis gene family and was originally identified from esophageal cancer." (PMID 37398650, 2023).
ovarian carcinoma (3 papers, 2015 to 2024). A malignant neoplasm originating from the surface ovarian epithelium. "Cancer testis antigen NY-ESO-1 (New York esophageal squamous cell carcinoma 1) is encoded by the CTAG1B gene, and expressed in 10–50% of metastatic melanomas, breast, prostate, thyroid, and ovarian cancers." (PMID 30621224, 2019).
esophageal squamous cell carcinoma (2 papers, 2019 to 2023). Esophageal squamous cell carcinoma (ESCC) is a type of esophageal carcinoma (EC) that can affect any part of the esophagus, but is usually located in the upper or middle third. "This has been demonstrated for classical CTAs, such as the MAGE family members and the New York esophageal squamous cell carcinoma‐1 (NY‐ESO‐1, gene symbol: CTAG1B), by the detection of autoantibodies in the serum of patients with a variety of cancer types." (PMID 37341056, 2023).
sarcoma (2 papers, 2013 to 2022). A usually aggressive malignant neoplasm of the soft tissue or bone. "Our results as well as those of others implicate Six1 in sarcoma growth however its functional links to CTAG1B/A or to RANBP2 remain to be established and underscore the complexity of sarcoma biology." (PMID 35664317, 2022). "We then re-constructed a ctag1b/a sarcoma network and used its properties to identify genes in the neighborhood of ctag1b/a." (PMID 35664317, 2022). "Using transcriptomics samples, we have extracted ctag1b/a co-expression modules from different tumor types in which ctag1b/a is re-expressed, and reconstructed a sarcoma ctag1b/a network." (PMID 35664317, 2022). "We confirmed expression of some of the ctag1b/a network neighbors in advanced grade sarcomas by using independent samples from the Department of Pathology at Aristotle University School of Medicine." (PMID 35664317, 2022). "Using different sarcoma samples, we immunohistochemically confirmed expression of some of the ctag1b/a network neighbors." (PMID 35664317, 2022). "CATs, including melanoma antigen, family A, 4 (MAGE-A4) and NY-ESO-1 (also known as CTAG1B, cancer/testis antigen 1B), have been shown to be overexpressed in certain carcinomas and sarcomas." (PMID 24649216, 2013). "We mapped CTAG1B/A protein to sarcoma transcription pathways with gene set expression analysis (GSEA) and using independent samples, we immunohistochemically identified expression of at least two network neighbors, RANBP2, and TLE1, thus validating our approach." (PMID 35664317, 2022). "We focused on sarcoma samples because they exhibited a distinct ctag1b/a expression pattern." (PMID 35664317, 2022). "Of the 1,245 gene sets in the MSig database, 1,171 are positively upregulated with ctag1b/, whereas only 74 of 1,245 are downregulated in the negative phenotype, suggesting that ctag1b/a re-activation is linked to many activated sarcoma pathways." (PMID 35664317, 2022). "Notable among the twenty five top genes found to be co-expressed with ctag1b/a in sarcomas are protocadherin β3, tumor necrosis factor alpha-induced protein 8-like 3, demethylase jumonji domain containing 2C, cyclin-dependent kinase 6, and glycine dehydrogenase (decarboxylating)." (PMID 35664317, 2022). "Ctag1b/a is enriched in transcription factor pathways, suggesting that it is likely a germ cell-specific transcription factor, that is, re-expressed, albeit randomly, in adult sarcomas and in various other tumors." (PMID 35664317, 2022). "We reasoned that by extracting gene and transcriptional modules that are co-expressed or co-regulated with ctag1b/a, we could map it to tumor pathways and use its network properties to identify network neighborhood genes that are also expressed in sarcoma samples." (PMID 35664317, 2022). "Interestingly, expression of CTAG1B/A and PRAME has recently been correlated with tumor grade and poor prognosis in myxoid sarcomas, supporting our hypothesis that CTAG1B/A is active in sarcoma biology." (PMID 35664317, 2022). "Using GSEA we extracted two phenotypic classes from a compendium of ten sarcoma types in two studies (GDS1209), representing gene modules whose co-expression pattern either correlates (CTAG1B/A-POS) or anti-correlates (CTAG1B/A_NEG) with ctag1b/a re-expression." (PMID 35664317, 2022).
synovial sarcoma (2 papers, 2022 to 2023). "Tle1 is notable not only for being an expression neighbor of ctag1b/a in the GSEA-identified module but also a network neighbor that has been proposed as a diagnostic immunohistochemical marker for synovial sarcoma." (PMID 35664317, 2022). "Lastly, the ssx2 gene, that is, found in the ctag1b/a subnetwork, is involved in 80% of all synovial sarcomas as fusion protein products SSXT-SSX1 or SSXT-SSX2, derived from translocation t (X; 18) (p11.2; q11.2)." (PMID 35664317, 2022). "On the other hand, staining for CTAG1B/A showed variable positivity of synovial sarcoma cells in six of seven cases." (PMID 35664317, 2022). "Immunohistochemical staining for MAGEC1, a protein, that is, found in intracellular complexes with CTAG1B/A, showed extensive (80%) positivity in synovial sarcoma cells in one of seven cases evaluated, whereas the remaining six cases were negative." (PMID 35664317, 2022). "Ctag1b/a is re-activated in synovial sarcomas and myxoid liposarcomas but not in differentiated liposarcomas." (PMID 35664317, 2022). "In contrast, in two studies (GDS2736 and GDS1209) almost all samples of stage 3 synovial sarcomas and myxoid liposarcomas uniformly express ctag1b/a whereas various differentiated liposarcomas do not show re-activation." (PMID 35664317, 2022). "Ctag1b/a was found to be significantly overexpressed (p < 10–7) in myxoid liposarcomas and synovial sarcomas but not in lipomas or leiomyosarcomas, a significant finding." (PMID 35664317, 2022).
esophageal (1 paper, 2022). "New York esophageal squamous cell carcinoma-1 (NY-ESO-1), also known as cancer testis antigen 1B (CTAG1B), is immunogenic and reportedly induces specific B- and T-cell immunity in patients with NY-ESO-1-expressing cancers." (PMID 35743725, 2022).
gastric cancer (1 paper, 2021). A primary or metastatic malignant neoplasm involving the stomach. "A different six-antigen panel, including CTAG1B/CTAG2, DDX53, IGF2BP2, P53P53, and MAGEA3, detected 13% of gastric cancer patients." (PMID 33672007, 2021).
lung adenocarcinoma (1 paper, 2020). A carcinoma that arises from the lung and is characterized by the presence of malignant glandular epithelial cells. "The NCI-H522 human lung adenocarcinoma cell line (H522) is of the HLA-A*02 type and expresses the CTAG1B gene, although at a low level compared to multiple other NSCLC cell lines." (PMID 32272797, 2020).
ovarian tumors (1 paper, 2023). "Lower levels of mRNA expression of genes of the 21 CTAs in ovarian tumors were detected for CTAG1A, CTAG1B, MAGEC1, and PIWIL2." (PMID 37835834, 2023). "For ovarian tumor samples, we detected six hub genes: GAGE2A, GAGE1, MAGEA9, CTAG1A, CTAG1B, and MAGEA1." (PMID 37835834, 2023).
prostate carcinoma (1 paper, 2012). A carcinoma that arises from epithelial cells of the prostate gland. "MAGE A1 and CTAG1B show a complex pattern of expression in samples of prostate carcinomas." (PMID 23145101, 2012).
soft tissue sarcoma (1 paper, 2024). A malignant neoplasm arising from muscle tissue, adipose tissue, blood vessels, fibrous tissue, or other supportive tissues excluding the bones. "Additionally, in a clinical trial (NCT04318964) investigating TCR-T cell therapy targeting CTAG1B, an ORR of 41.7% was observed across breast, liver, ovarian, and soft tissue sarcoma cancers." (PMID 39439803, 2024).
cancer (20 papers, 2014 to 2025). A tumor composed of atypical neoplastic, often pleomorphic cells that invade other tissues. "The expression of two cancer-associated testis antigens CTAG1B and MAGE-C1 genes was used as a positive control, since their promoters are known to be controlled by DNA methylation." (PMID 26848772, 2016). "The researchers found that the modified TCR-T cells specifically recognized CTAG1B, activated T cells, and significantly inhibited cancer cell proliferation in an in vitro model." (PMID 39439803, 2024). "Cancer/testis antigen 1B (CTAG1B), also known as New York esophageal squamous cell carcinoma 1, is the third most common antigen in CanVaxKB, which targets multiple types of cancers." (PMID 38204924, 2024). "The favorable response rates observed in these trials ranged from 35.7% to 66.7%, highlighting the importance of continued exploration of CTAG1B-targeted therapies, especially in cancers with limited therapeutic options." (PMID 39439803, 2024). "Ctag1b/a was the first cancer testis antigen gene to be discovered in cancer patients using an in vivo antibody response and successfully targeted by a vaccine." (PMID 35664317, 2022). "CTAG1B (cancer/testis antigen 1B) - is a member of cancer/testis (CT) antigens found expressed in normal testis and in many cancers." (PMID 25077705, 2014). "These consistent findings suggest that targeting well-characterized antigens like CTAG1B can significantly impact the therapeutic landscape for cancer, reinforcing the importance of ongoing research and development in TCR-T cell therapies to maximize clinical outcomes." (PMID 39439803, 2024). "Top three mostly used canvaxgens are PMEL, MLANA and CTAG1B, often targeting multiple cancer types." (PMID 38204924, 2024). "NY-ESO-1 (also known as cancer/testis antigen 1B, CTAG1B) is an immunogenic member of the cancer/testis antigen family—a protein family with germ and cancer cell expression patterns—showing nuclear localization in mesenchymal stem cells and predominately cytoplasmic expression in tumor cells." (PMID 32391000, 2020). "Several CTAs of our panel, such as the MAGE-family members, CTAG1B, TSPY1, and CAGE1, are functionally involved in tumorigeneses and cancer progression by modulating gene expression, regulating mitosis, and tumorigenic signaling." (PMID 34065388, 2021). "The CTA New York oesophageal squamous cell carcinoma-1 (NY-ESO-1), also known as cancer-testis antigen 1B (CTAG1B), is immunogenic and reportedly induces specific B-cell and T-cell immunity in patients with NY-ESO-1-expressing cancers." (PMID 34359776, 2021). "CTAG1B (also known as NY-ESO-1) is a well-known CT antigen eliciting humoral and cellular immune response in patients with various cancers including BC." (PMID 30515157, 2018). "Additionally, other autoantibodies targeting SOX2, HIF1-α, NY-ESO-1/CTAG1B, MUC1, Her2, GAL1, and GAL3 have been frequently identified in cancer patients." (PMID 37627091, 2023). "Not surprisingly, several cancer testis antigens (CTA) including CT45A1, CT45A3, CT45A5, CTAG1B and CTAG2 were highly expressed in TNB-High or TMB-High tumors." (PMID 41562064, 2025).
tumor (11 papers, 2015 to 2025). "Two DEGs were identified for both the Group B/trastuzumab-sensitive models (tumor-specific antigens CTAG1B, MAGEC1) and the Group C/all treatment-sensitive models (HLA-DRB5, RNL5)." (PMID 37749105, 2023). "Accordingly, CTAG1B-overexpressing tumours showed improved response to PD-1 blockade compared with control tumours." (PMID 36732592, 2023). "IHC demonstrated that Rnf43 knockdown impaired DC and CD8+ T cell infiltration even in CTAG1B-overexpressing tumours." (PMID 36732592, 2023). "Similarly, other tumor antigens like CTAG1B have also shown great potential in advancing immunotherapy." (PMID 39439803, 2024). "NY-ESO-1 (product of the CTAG1B gene) is perhaps the best characterised member of this family, and may be selectively expressed by cancer stem cells and is expressed in the tumours of approximately 40% of ovarian cancer patients." (PMID 32937961, 2020). "However, Rnf43 knockdown abolished the efficacy against CTAG1B-overexpressing tumours." (PMID 36732592, 2023). "CTAG1B has emerged as a primary target for TCR-T therapy, with clinical trials demonstrating its strong anti-tumor activity, especially in STS." (PMID 39439803, 2024). "The examination indicated the hub genes in tumor samples, including GAGE2A, GAGE1, MAGEA9, CTAG1A, CTAG1B, and MAGEA1; and the hub genes in healthy ovarian tissue samples, including SPA17, MAGEC1, KDM5B, SSX4, and MAGEA9." (PMID 37835834, 2023). "These CTAs were expressed by tumor cells, similar to MAGEA10, MAGEC1, and CTAG1B proteins as demonstrated in our previous study." (PMID 34065388, 2021). "Notably,CTAG1B (also known as NY-ESO-1), the CTA with clinical efficacy as animmunotherapeutic target, was required for tumour cell proliferation." (PMID 26567849, 2015). "The analysis of the mRNA expression levels of 21 CTAs in healthy and tumor ovarian tissue showed an up-regulation in the expression level of AKAP3, MAGEA4, PIWIL1, and PRAME in tumor samples and a down-regulation in the expression level of CTAG1A, CTAG1B, MAGEC1, and PIWIL2." (PMID 37835834, 2023).
CTAG1B also shares sentences with these, for which no sentence is quoted: breast carcinoma (1 paper); glioblastoma (1); leiomyosarcoma (1); lipoma (1); liposarcoma (1); liver cancer (1); myxoid liposarcoma (1); thyroid cancer (1).